RNU1-29P (RNA, U1 small nuclear 29, pseudogene)
Gene: Small nuclear RNA gene on chromosome 7 (120,005,976 to 120,006,101, reverse strand). Ensembl gene ENSG00000271739.
Homologues: Orthologues: chimpanzee U1 (99% identical), guinea pig U1 (79% identical), dog U1 (78% identical). Paralogues in human: RNU1-1 (88% identical), RNU1-2 (88% identical), RNU1-27P (88% identical), RNU1-28P (88% identical), RNU1-3 (88% identical), RNU1-4 (88% identical), RNVU1-18 (88% identical), RNVU1-29 (88% identical), RNVU1-7 (88% identical), U1 (88% identical), RNVU1-28 (87% identical), RNU1-11P (87% identical), and 134 more.